ACSL4 (acyl-CoA synthetase long chain family member 4)
Diseases named in the same sentence as ACSL4 in open-access papers (continued):
Sharing a sentence is not in itself a finding about the gene and the disease.
tumor (continued). "ACSL4 was found to act as a tumor suppressor and promoted ferroptosis." (PMID 37158834, 2023). "Moreover, ACSL4 knockdown in shCARM1 tumors significantly increased tumor weight and reduced MDA and lipid peroxide levels." (PMID 37946697, 2023). "Previous studies have reported that ACSL4 could act as a tumor suppressor or oncogene, depending on the specific cancer type and tissue environment." (PMID 38078907, 2023). "C16 and C18 can promote ACSL4-dependent tumor ferroptosis induced by IFN-γ and AA." (PMID 37894808, 2023). "However, ACSL4 is regarded as playing complex roles in tumor promotion and tumor suppression in different cancer types, while it plays important parts in lipid metabolism reprogramming, which shows different effects on tumors." (PMID 37509438, 2023). "Furthermore, the expression of ACSL4 was significantly negatively correlated with RNF25 protein expression in CRC tumor tissues of patients." (PMID 37946697, 2023). "We identify acyl-CoA synthetase long-chain family member (ACSL4) as an miR-211 target, explaining the observed downstream effects of miR-211 on lipid metabolism through a tumor suppressive lipid phenotype of reduced long-chain fatty acids and increased polyunsaturated fatty acids." (PMID 38115140, 2023). "ACSL4 is significantly upregulated in tumor cells, particularly on the membranes of tumor cells." (PMID 37372148, 2023). "Based on HPA database, immunohistochemical analysis showed strong ACSL4 staining in tumor tissues." (PMID 37193981, 2023). "Interestingly, knockdown of ACSL4 restored the expression of E-cadherin, an essential adhesion molecule, indicating that ACSL4 promotes tumor invasion through multiple mechanisms." (PMID 38078907, 2023). "More importantly, according to our analysis, GPX4 and ACSL4 are significantly associated with various oncogenesis-related signaling pathways, such as the tumor proliferation signature pathway, the EMT, angiogenesis and the tumor inflammation signature pathway." (PMID 37739961, 2023). "Overexpression of ACSL4 is believed to promote tumor cell proliferation and invasion." (PMID 37372148, 2023). "Moreover, the gastrodin treatment led to decreased levels of KI67 and PCNA protein expression and increased levels of HOXD10 and ACSL4 in the tumor tissues compared to the DMSO treatment." (PMID 38138552, 2023). "Interestingly, erastin or IKE treatment significantly increased the expression of ACSL4 in tumor tissues as compared with saline-treated controls, but these effects were remarkably suppressed by MI." (PMID 36967385, 2023). "Accordingly, targeting ACSL4 or LPCAT to modulate ferroptosis in tumor therapy could affect tumor development and survival." (PMID 36976734, 2023). "Subsequently, we validated the role of ACSL4 in CARM1‐induced tumor growth in vivo." (PMID 37946697, 2023). "Moreover, recent research found that AA played an antitumour role in three ways: promoting tumour cell ferroptosis induced by ACSL4, elevating the antitumour CD8+ T-cell response and sensitizing tumour cells to checkpoint therapy." (PMID 36243728, 2022). "This prompted the authors to further examine whether ACSL4 is engaged in CD8+ T-cell-mediated anti-tumor immunity." (PMID 35459217, 2022). "Recent studies suggested that ACSL4 may play a tumor-suppressive role and serve as a therapeutic target in the treatment of GC." (PMID 36497375, 2022). "Therefore, the expression of ACSL4 can inhibit the migration and invasion of GC, which illustrates that ACSL4 can be a potential therapeutic target as a tumor suppressor in GC." (PMID 35237519, 2022). "The investigation of expression of ACSL4 in HCC tumor specimens revealed that the high baseline expression of ACSL4 in untreated HCC tissue is related to complete or partial responses to sorafenib treatment in comparison to the HCC group with low ASCL4 expression." (PMID 35406596, 2022). "ACSL4 was also significantly down-regulated in tumor tissues compared with matched normal tissues." (PMID 35321435, 2022).
tumor (continued). "Specifically, ACSL4 participates in ferroptosis, a promising target for tumor therapeutics." (PMID 35910359, 2022). "IFN-γ regulates the expression of ACSL4 (Acyl-CoA synthetase long chain family member 4) directly through STAT1-IRF1 signaling pathway, while arachidonic acid induces ferroptosis in tumor cells through preferential integration of ACSL4 into phospholipids containing C16 and C18 acyl chains." (PMID 36387147, 2022). "Tumor inhibition was greater when erastin was paired with Hsp90 or Acsl4 overexpression." (PMID 35697672, 2022). "However, in BRCA, ACSL4 expression levels were significantly negatively correlated with tumor purity, suggesting sustained enrichment of ACSL4 in tumor cells." (PMID 35126480, 2022). "Patients with BLCA and elevated ACSL4 levels had better prognoses and suppressed tumor progression." (PMID 36497375, 2022). "In addition, IFNγ secreted by CD8+ T cells, which are activated by immunotherapy binds to IFNR, activates the JAK-STAT1-IRF1 signaling axis, and induces the expression of ACSL4 in tumor cells." (PMID 35847985, 2022). "Several studies suggested the tumor-promoting role of ACSL4 in cancer development." (PMID 35368896, 2022). "Our study implies that ferroptosis may take place in GBM tumor cells due to the profound changes in the expression of ACSL4 and GPX4." (PMID 35530303, 2022). "Moreover, previous studies found that ACSL4 had certain effects on cancer progression, recurrence, and prognosis, and was expected to become an available tumor biomarker and therapeutic target." (PMID 35910359, 2022). "Studies have identified a pro-tumor metastatic effect of ACSL4 in CRC." (PMID 36497375, 2022). "Therefore, the ACSL4 signaling pathway that targets ferroptosis in the tumor microenvironment is favorable to enhance the therapeutic efficacy of ICB." (PMID 35847022, 2022). "Considering that ACSL4 is genetically altered in a variety of cancers, we further analyzed whether there is a correlation between ACSL4 gene alteration or epigenetic modification and tumor immune cell infiltration level by using TIMER database." (PMID 35126480, 2022). "The dysregulation of ACSL3 and ACSL4, which belong to the five isoforms of ACSLs, plays a key role in cancer initiation, development, metastasis, and tumor immunity and may provide several possible therapeutic strategies." (PMID 36497375, 2022). "In addition, some studies have shown that miR-424-5p negatively regulates tumor-induced hypertrophy by directly targeting acyl-CoA synthetase long chain family member 4 (ACSL4) in OV cells, and subsequently reduced erastin- and RSL3-induced ferroptosis." (PMID 35409396, 2022). "Moreover, the amount of Iba1+ cells of ACSL4+ cells was three to four times lower in the primary tumor and decreased significantly by an average of 6.1% in the recurrent tumor (p=0.026)." (PMID 35530303, 2022). "Functionally, ACSL4 knockdown could induce decreased cell proliferation, whereas upregulation ACSL4 expression could activate tumor formation in vitro and in vivo." (PMID 35910359, 2022). "IFNγ from CD8+ T cells and arachidonic acid (AA) from the tumor microenvironment mediate tumorigenic ferroptosis through acyl-CoA synthetase long-chain family member 4 (ACSL4) while targeting tumor ACSL4 reportedly improved immune checkpoint blockade treatment sensitivity." (PMID 36158661, 2022). "Specifically, activation of ACSL4 may play a role in lipid metabolism reprogramming, providing an efficient supply for tumor survival, or inducing antitumor effects leading to tumor death." (PMID 35910359, 2022). "CD8 + T cells and fatty acids orchestrate tumor ferroptosis and immunity via ACSL4." (PMID 35610340, 2022). "In vivo experiments demonstrated that knockdown of ACSL4 could improve the ability of tumor invasiveness and inhibit ferroptosis, while ACSL4 overexpression represented the opposite effects." (PMID 35910359, 2022). "The ACSL4 and miR-454-3p expression in tumor samples and normal tissues were evaluated." (PMID 35368896, 2022).
tumor (continued). "Recent studies have shown that ACSL4 expression changes in a variety of cancers, and targeting at ACSL4 could affect tumor progression, suggesting that ACSL4 may be a potential tumor marker and therapeutic target." (PMID 35910359, 2022). "Moreover, analysis on collected RCC tumor samples and healthy tissues also showed elevated expression of ACSL4 in RCC tumors." (PMID 35368896, 2022). "In the current study, we found that the expression level of ACSL4 in BLCA was positively correlated with tumor infiltration of CD8+ T cells, which may affect the efficacy of immunotherapy in BLCA patients." (PMID 34868963, 2021). "Knockdown of ACSL4 expression can significantly attenuate the lipid peroxidation and ferroptosis induced by sorafenib in Huh7 cells and save the sorafenib-induced growth inhibition of xenograft tumours in vivo." (PMID 34418989, 2021). "In addition to regulating ACSL4 expression, it is clear that IR can directly target the tumor cell membrane PUFA-PL by generating an abundance of ROS." (PMID 34249928, 2021). "With regard to HCC, previous work has demonstrated that increased ACSL4 may be a determinant of drug resistance and increased tumour growth." (PMID 32286604, 2020). "Similarly, at necropsy, the excised tumor weights were significantly suppressed in ACSL4-depleted group compared to negative control with decreased expression of c-Myc and ACSL4." (PMID 32350243, 2020). "Furthermore, we found that overexpression of miR-211-5p inhibited ACSL4 expression in a xenograft tumor model." (PMID 32859232, 2020). "Secondly, it was confirmed that miR-211-5p served as a tumor suppressor in HCC by targeting ACSL4, although the underlying mechanism of the promotion of cell proliferation, invasion, and migration by ACSL4, remains unclear." (PMID 32859232, 2020). "In summary, these results demonstrated that miR-211-5p may act as a tumor suppressor in HCC by targeting ACSL4." (PMID 32859232, 2020). "Furthermore, exploration of enzymes revealed that ACADSB (which was also highlighted by previous analyses), ACSL3, and ACSL4 regulate proteins that stimulate tumor cell proliferation, including p-AKT, LSD1, and β-catenin." (PMID 33424926, 2020). "The ACSL4/LPCAT3/15-LOX axis not only oxidize AA or AdA to LPO to elicit ferroptosis but also may produce “find me” signals from ferroptotic tumor cells, mediating antitumor immunity." (PMID 32606298, 2020). "Importantly, high levels of ACSL1 and/or ACSL4 expression in patient tumor samples correlates with a worse prognosis." (PMID 31344914, 2019). "Mechanistic studies demonstrated that combining sorafenib and aspirin yielded significant synergistically anti-tumor effects by simultaneously silencing ACSL4 and the induction of GADD45B expression in HCC cells both in vitro and in the orthotopic HCC xenograft mouse model." (PMID 28900541, 2017). "A similar correlation is seen with respect to ACSL4 mRNA expression in human tumor samples." (PMID 24155918, 2013). "We also aimed to determine whether a combinatorial inhibition of the ACSL4-LOX-COX-2 pathway affects tumor growth in vivo on MDA-MB-231 tumor xenografts." (PMID 22808264, 2012). "The data presented here showing a synergistic inhibitory effect on tumor growth by ACSL4, LOX-5 and COX-2 inhibitors with the use of lower doses of the respective drugs may also result in the reduction of potentially severe side-effects." (PMID 22808264, 2012). "We also aimed to determine whether a combinatorial inhibition of the ACSL4-LOX-5-COX-2 pathway affected tumor growth in vivo." (PMID 22808264, 2012). "This study was undertaken to confirm the effect of ACSL4 overxpression on tumor growth in vivo." (PMID 22808264, 2012). "The MCF-7 Tet-Off/ACSL4 tumor xenografts, the MCF-7 Tet-Off empty vector tumor xenografts, and the MCF-7 Tet-Off/ACSL4 tumor xenografts treated with doxicycline were isolated, stained with hematoxylin–eosin and analyzed under light microscopy in order to define the histology of the tumors." (PMID 22808264, 2012).
tumor (continued). "On one hand, ACSL4 amplifies lipogenic transcriptional programs, enhances fatty acid oxidation-mediated energy adaptation, and cooperates with oncogenic signaling networks to promote tumor proliferation and survival, particularly under nutrient stress such as transarterial chemoembolization (TACE)." (PMID 42064086, 2026). "The tumor immune microenvironment plays a central role in modulating ferroptosis susceptibility: CD8+ T cell-derived IFNγ downregulates system Xc- and upregulates ACSL4, while other immune cells such as Tregs, MDSCs, and macrophages further fine-tune ferroptosis through cytokine and redox signaling." (PMID 41607787, 2026). "Notably, Lysophosphatidylcholine Acyltransferase 3 (LPCAT3) and LOX are respectively involved in the incorporation of arachidonic acid into membrane phospholipids and the oxidation of these phospholipids, collectively promoting ACSL4-dependent tumor ferroptosis induced by IFN-γ and arachidonic acid." (PMID 41035634, 2025). "Finally, exploring the broader impact of ACSL4 inhibition on tumor microenvironment interactions, such as immune evasion or stromal support, may reveal additional therapeutic opportunities in ER-positive breast cancer." (PMID 40507798, 2025). "Similarly, exosomal ferroptosis-related protein markers (GPX4, ACSL4) and lipid peroxidation products (4HNE) may also reflect tumor cell ferroptosis activity and serve as potential tumor diagnostic tools." (PMID 40328736, 2025). "Furthermore, enhancing tumor apoptosis through ACSL4 inhibition and targeted acetylation of signal transducer and activator of transcription 3 (STAT3) was associated with a reduction in mitochondrial membrane PLs, providing a critical strategy to overcome cancer cell chemoresistance." (PMID 41288931, 2025). "Furthermore, T cell-derived IFN-γ can further stimulate ACSL4 activity and alter the tumor cell lipid profile, consequently increasing the incorporation of arachidonic acid (AA) into phospholipids enriched with C16 and C18 acyl chains, ultimately inducing immunogenic tumor ferroptosis." (PMID 40260246, 2025). "Notably, inhibiting the ferroptosis regulators CHAC1 and ACSL4 in A375 cells reversed these effects, highlighting ferroptosis as a critical mediator of T-cell activation, potentially through the release of immunogenic signals from dying tumor cells." (PMID 40860143, 2025). "In combination with the constructed hybridized arachidonic acid containing nanovesicles (MLipoAA), pre-activation of the T cell immunity could effectively direct tumor cell ferroptosis mediated by IFN-γ-Acsl4 nexus, inducing prominent tumor destruction with immunopotentiation." (PMID 41254669, 2025). "For instance, modulating lipid metabolic pathways with existing inhibitors targeting LPCAT1 or ACSL4 may disrupt aberrant lipid flux within tumor cells, impeding tumor growth and overcoming chemoresistance, while LCAT inhibitors could impair membrane integrity and energy homeostasis in HCC cells." (PMID 40500772, 2025). "Because phosphorylation of different sites on ACSL4 may confer distinct biological effects, with mass spectrometric analysis, we found that the T679 residue phosphorylation level of ACSL4 was markedly decreased in HONE1-derived TRCs compared to bulk tumor cells." (PMID 38720107, 2024). "Interestingly, in a novel study, researchers reported that ACSL4 deficiency prevents ferroptotic cell death in hepatocytes but does not aggravate tumour progression and instead results in less fibrosis and proliferation." (PMID 38993573, 2024). "In addition, IFN-γ can also synergize with AA to induce ferroptosis of immunogenic tumor cells in an ACSL4-dependent mechanism Combined with ferroptosis inhibitors and immunotherapy with PD1 could further inhibit tumor growth." (PMID 39359721, 2024). "Importantly, in the context of hepatocellular carcinoma, ACSL4-dependent mechanisms may have both tumor-promoting and tumor-inhibitory effects." (PMID 37840106, 2023).
tumor (continued). "Thus, we confirmed that ACSL4 expression is upregulated in CHOL tumor tissues." (PMID 37193981, 2023). "However, ACSL4 is critical for arachidonic acid metabolism in tumor cells." (PMID 37372148, 2023). "Therefore, ACSL4 could play complex roles in tumor promotion and tumor suppression when analyzing different tumors." (PMID 35910359, 2022). "Moreover, an ACSL4 depletion showed inhibiting effects on GBM tumor cell growth." (PMID 35530303, 2022). "Therefore, ACSL4 could become a promising drug target for certain tumor treatment via ferroptosis pathway." (PMID 35910359, 2022). "It has recently been shown that Acyl-CoA Synthetase Long Chain 4 (ACSL4) enhances the expression of lipogenic enzymes through the c-Myc/SREBP1 oncogene signaling; however more studies are needed to determine the association between ACSL4, metabolism and tumor lipid abnormalities." (PMID 35198567, 2021). "Given that fatty acid metabolism is widely involved in tumorigenesis and cancer progression, ACSL4 might catalyze different kinds of fatty acid substrates in different cancer types, thereby re-programming the cell metabolomics to be either tumor-promoting or tumor-inhibiting." (PMID 34053456, 2021). "However, when ACSL4 was partially depleted, there was little inhibition of tumor growth (sh#42)." (PMID 33110073, 2020). "Notably, tumor growth was dampened when ACSL4 expression was more effectively silenced (sh#41)." (PMID 33110073, 2020). "Prostate stromal cells normally express ACSL4, so we next questioned whether expression of ACSL4 in prostate stromal cells might influence the growth of neighboring tumor cells through paracrine signaling, possibly such as by prostaglandin E2 (PGE2) production." (PMID 26636648, 2015). "On the other hand, ACSL4-driven enrichment of PUFA-containing phospholipids establishes the biochemical foundation for ferroptosis, sensitizing tumor cells to sorafenib and CD8+ T cell-mediated oxidative killing." (PMID 42064086, 2026). "Further mechanistic investigations reveal that KLF1 inhibits ACSL4 expression via transcriptional repression and suppresses ferroptosis through the ACSL4/LPCAT3 axis, ultimately promoting HCC tumour growth as well as its advancement." (PMID 41656392, 2026). "We further demonstrated that ACSL4, a long-chain fatty acid-CoA ligase, was upregulated by the JAK/STAT pathway in enzalutamide-resistant SCL/NEL cells, thereby facilitating tumor proliferation and metastasis while increasing sensitivity to ferroptosis." (PMID 42215431, 2026). "This synergy was robustly validated in a U2OS xenograft model, where the combination of (20S)-PPT and IKE achieved a superior 74% reduction in tumor volume compared to IKE monotherapy (42%), accompanied by confirmed upregulation of ACSL4 in tumor tissues." (PMID 41471274, 2025). "ACSL4, low in EOC, suppresses tumor growth by inducing ferroptosis and M1 macrophage polarization, counteracting USP7-driven antiferroptosis and M1 suppression." (PMID 41280929, 2025). "In NSCLC, combining ROR1 CAR-T cells with ferroptosis inducers enhances tumor cell ferroptosis by increasing IFN-γ secretion, lipid peroxidation, and ACSL4 upregulation, thereby promoting robust antitumor responses." (PMID 40919170, 2025). "IHC analysis showed that the K383R of ACSL4 reduced the positive rate of 4-HNE and Ki67 in tumor cells." (PMID 40050614, 2025). "High expression of RRFERV also regulates the ACSL4/TFRC axis, maintaining an exquisitely balanced redox state in tumor cells, which renders them particularly sensitive to ferroptosis." (PMID 40919170, 2025). "We show that BQ disrupts the NCOR2-PPARγ interaction, leading to ACSL4 upregulation, which enhances fatty acid oxidation (FAO), acetyl-CoA by 1.8-fold, and ATP production by 2.5-fold to fuel tumor proliferation." (PMID 40507798, 2025).